INS (insulin)
Diseases named in the same sentence as INS in open-access papers (continued):
Sharing a sentence is not in itself a finding about the gene and the disease.
Obesity (continued). "Insulin-stimulated TBC1D4 (Thr642) phosphorylation exhibited a trend to be repressed with obesity (P = 0.10); this difference became more evident after resveratrol treatment in pThr642 and pSer704 (P < 0.05)." (PMID 38324260, 2024). "Primary human myotubes maintain the metabolic phenotype of the donor; for example, we have reported that myotubes derived from individuals with severe obesity are insulin resistant and exhibit decrements in fatty acid oxidation." (PMID 38324260, 2024). "Both Mlkl−/− and Mlkl+/− mice on the HFHFrHC diet resisted diet-induced obesity, attributed to the increased beiging, enhanced oxygen consumption, and energy expenditure due to adipose tissue, and exhibited improved insulin sensitivity." (PMID 38474061, 2024). "The adiposity and/or obesity exacerbate insulin dysregulation and create a pro-inflammatory microenvironment, fostering systemic and regional inflammation." (PMID 38689728, 2024). "We were able to show that GH insensitivity impedes β-cell maturation and function and that the GHR-KO pig resembles the phenotype of human Laron syndrome (LS) patients who display increased insulin sensitivity despite obesity." (PMID 38960990, 2024). "The main finding of this study was that resveratrol treatment improved insulin-mediated glucose metabolism in myotubes from lean individuals and/or individuals with severe obesity." (PMID 38324260, 2024). "Given the elevated insulin levels and prevalence of hyperinsulinemia, clinicians should consider incorporating regular insulin screening into routine evaluations for children with severe obesity." (PMID 39407760, 2024). "are suspected to mediate anti-obesity effects through enhancement of fat thermogenesis, maintenance of gut integrity, and reduction of the serum insulin resistance level." (PMID 38375198, 2024). "Lifestyle factors that stimulate insulin secretion, such as overweight/obesity, low fruit and vegetable intake, and high red meat consumption, are also risk factors for digestive tract cancers, especially CRC." (PMID 39103728, 2024). "GLP-1RA ever-users (33 386 individuals [6.1%]) were on average younger (t14 314 = 48.1) with a greater proportion of obesity (χ23 = 6433) than basal insulin ever-users (106 849 individuals [19.7%])." (PMID 38175642, 2024). "While it is not possible to establish causal relationships with the applied methods, the results highlight the role of insulin and glucose metabolism in alterations in brain metabolites often seen in obesity." (PMID 37824728, 2024). "The mechanism underlying the association between obesity, related metabolic abnormalities, and depression may involve the alterations in adipose-related metabolic signals, including glucocorticoids, adipose-derived hormones, and insulin and inflammatory cytokines." (PMID 38418418, 2024). "Fat is a multifunctional tissue that is significant in balancing energy equilibrium within the body and insulin sensitivity; however, its excessive accumulation can lead to obesity, inflammation, and other metabolic diseases." (PMID 39631563, 2024). "Propionate administration for 22 weeks reduced hepatic lipogenesis and improved insulin sensitivity in a diet-induced obesity mouse model." (PMID 39064765, 2024). "In the liver, Mir802 is induced by obesity and impaired glucose tolerance, and it attenuates insulin sensitivity by downregulation of Hnf1b." (PMID 39589393, 2024). "This study aims to estimate the effects of long-term taurine supplementation on blood lipids, glycemia, and insulin sensitivity in adults with overweight or obesity through a systematic review and meta-analysis." (PMID 39796489, 2024). "Chronic tissue inflammation is now recognized as an essential characteristic of obesity and T2D, affecting insulin-target tissues such as adipose tissue, liver, muscle, and heart." (PMID 38988822, 2024). "In this respect, perhaps, obesity and insulin sensitivity, or resistance stand out as compared to other NCDs." (PMID 39472276, 2024).
Obesity (continued). "Phytocannabinoids have been found to reduce obesity, inhibit chronic inflammation, lower fasting insulin levels and insulin sensitivity, and thus possess direct anti-tumor effects." (PMID 38256042, 2024). "Butyric acid can promote the release of gastrointestinal peptide hormones such as peptide YY (PYY) and glucagon-like peptide-1 (GLP-1), thus improving obesity and insulin sensitivity induced by a high-fat diet." (PMID 38257160, 2024). "Plasma levels of palmitic acid (PA) are elevated in obesity, triggering inflammation and disruption of insulin signaling." (PMID 38794136, 2024). "In obesity, cells in the body stop responding adequately to insulin, leading to elevated insulin levels in the blood." (PMID 38655176, 2024). "DTG is also known to affect the level of cellular insulin interfering with lipid metabolism, resulting in obesity among patients." (PMID 38182720, 2024). "Insulin/insulin-like growth factor-1 (IGF-1) signaling has been shown to be a critical arbitrator in obesity-related EAC." (PMID 39335147, 2024). "aimed to assess the relationship between IL-1β/Caspase-1, insulin sensitivity and early-stage obesity-related renal damage, namely hyperfiltration." (PMID 39469576, 2024). "The concentration of BCAAs has been found to be increased in individuals with obesity, and was positively correlated with the visceral fat and insulin resistance." (PMID 38535297, 2024). "Obesity induces a variety of systemic changes, including altered levels of insulin, insulin-like growth factor-1 (IGF-1), leptin, adiponectin, steroid hormones, and cytokines, creating an environment that favors tumor initiation and progression." (PMID 39630839, 2024). "Activation of PPARα, a liver-predominant member of the peroxisome proliferator-activated receptors (PPARs), leads to reductions in triglyceride levels, ameliorates obesity, and inhibits liver fatty degeneration, thereby enhancing insulin sensitivity." (PMID 39201413, 2024). "The transition from obesity to liver disease involves complex metabolic and inflammatory events, with insulin resistance playing a central role by disrupting glucose and lipid metabolism." (PMID 39402270, 2024). "Osteocalcin (OC), which is lower in obese subjects and is considered a bone formation marker, improves glucose intolerance, obesity, and insulin expression by controlling gene expression in β-cells and adipocytes." (PMID 38732046, 2024). "There appear to be a number of situations that either facilitate or hinder this transport, ultimately influencing insulin availability within the brain: insulin penetration into the CSF is lower in individuals with obesity." (PMID 38363340, 2024). "Elevation of CCL2 in the adipose tissue of patients with obesity attracts monocytes, resulting in inflammation and insulin resistance within the adipose tissue." (PMID 39334887, 2024). "The association persisted after adjustments for age, sex, smoking, obesity, insulin therapy, hypoglycemic agents’ medication, and some biochemical parameters." (PMID 38997409, 2024). "In general, our ex vivo assays suggest that incubation with insulin induces an obesity-like metabotype in healthy controls, as most differential metabolites experienced a change toward the levels detected in children with obesity." (PMID 39261864, 2024). "Similar effects have been reported with major urinary protein (MUP1) in modulating insulin sensitivity and glucose metabolism in obesity." (PMID 38673873, 2024). "For most of these metabolic and regulatory relationships, there is a considerable amount of proving information already available, especially in the references to insulin function and the maintenance of glycaemia, together with the closely related obesity." (PMID 38396928, 2024). "This suggests that exercise can lower obesity, raise serum irisin levels, and enhance insulin sensitivity." (PMID 39290329, 2024).
Obesity (continued). "It highlights two key complementary models: the energy balance model and the more comprehensive carbohydrate-insulin model, to understand the development of obesity and metabolic dysfunctions." (PMID 38884643, 2024). "In obesity, hypertrophic adipocytes trigger inflammation, fibrosis, and hypoxia, whereas smaller adipocytes exert favorable metabolic effects, contributing to insulin sensitivity." (PMID 38721091, 2024). "Diabetic patients typically present four metabolic abnormalities: abnormal insulin action, dysfunctional insulin secretion, increased endogenous glucose output, and obesity." (PMID 39595541, 2024). "A recent study has provided evidence indicating that there is a correlation between the aggravation of SRBDs and the progressive rise in insulin resistance among children with simple obesity and patients with PWS treated with rhGH." (PMID 38200464, 2024). "RBP4 is primarily produced by the liver and adipose tissue, and its expression is elevated in insulin-resistant mice and humans with obesity and type 2 diabetes." (PMID 38672227, 2024). "In the present targeted analysis of the canonical insulin signal pathway in obesity with RNAseq only one gene, IRS1, displayed statistically significant sex difference showing decreased expression in men." (PMID 38491191, 2024). "This network features several remarkable overlaps, both with the cytokine storm observed in viral infections and exacerbated in obesity, as well as insulin-resistant metabolic conditions." (PMID 38672413, 2024). "Sucralose, while effective in maintaining glucose levels in healthy individuals, has been shown to increase insulin AUC in people with obesity, potentially affecting insulin sensitivity." (PMID 39583955, 2024). "Affected individuals usually consume additional food, leading to obesity, a condition that can potentially disrupt insulin sensitivity." (PMID 38274329, 2024). "In modern society, high-fat diets, excessive sugar intake, sedentary lifestyles, and staying up late are critical contributors to insulin resistance and the exacerbation of obesity in children and adolescents." (PMID 40302954, 2024). "Obesity promotes muscle breakdown through insulin resistance, leading to a decline in both muscle mass and strength, consequently causing sarcopenia." (PMID 38674866, 2024). "When hepatic glycogen stores are saturated in obesity, hepatic insulin resistance drives gluconeogenesis from multiple precursors, including lactate, pyruvate, glycerol, glutamine anaplerosis, and propionate." (PMID 39063184, 2024). "Obese conditions may pose a significant challenge in maintaining stable BP, general obesity (described as BMI), and abdominal fat (described as WC) and may increase the risk of high BP due to an elevated volume of fatty acid release amplified by insulin resistance and the release of adipokine." (PMID 39125283, 2024). "In our study, the majority (67.1%) of the women were living with obesity, limiting the potential for further increases in body fat and related changes in glycaemic and insulin parameters." (PMID 39763542, 2024). "Adiponectin is known for its anti-inflammatory and insulin-sensitizing properties, and its level reduces in obesity." (PMID 38999854, 2024). "Although macrophage insulin signalling is impaired in obesity and T2D, insulin-resistant macrophages have increased glucose uptake, glycolysis, and glucose oxidation." (PMID 38988822, 2024). "Chronic genistein treatment is also known to improve insulin action in peripheral tissues, resulting in a glucose-lowering effect in obesity." (PMID 39201705, 2024). "For instance, body weight varied substantially across mice and correlated significantly with 25% of Strain- and Diet-affected phosphopeptides, suggesting obesity-related systemic factors likely impact a subset of the muscle insulin signalling network." (PMID 38329473, 2024).
Obesity (continued). "miRNAs are also involved in lipid metabolism, inflammation, and insulin signaling in the liver and are altered with obesity progression." (PMID 39684547, 2024). "These mice were found to be resistant to obesity resulting from a high-fat diet and demonstrated heightened insulin sensitivity." (PMID 38982993, 2024). "Other lipids, such as DAG, an immediate precursor of TAG elevated in muscles and liver of patients with obesity and T2DM, have been associated with declined insulin sensitivity through dysfunctional modification of insulin signaling molecules." (PMID 37152942, 2023). "MOTS-c plays roles in obesity, insulin resistance, exercise, inflammation and lifespan through retrograde signaling affecting nuclear gene expression (such as the AMPK pathway and pro-inflammatory factors)." (PMID 36670507, 2023). "Adipose tissue is an important reservoir of energy in the body, but its excessive accumulation contributes to the development of obesity in part by promoting a proinflammatory, hyperlipidemic, and insulin-resistant environment." (PMID 37071471, 2023). "In sum, deficiency for CerS6 in POMC neurons attenuates the diet-dependent effects on mitochondrial morphology in male mice, increases POMC neuron leptin sensitivity, and improves the insulin-dependent regulation of glucose metabolism in obesity." (PMID 38016943, 2023). "Once present, which is very common in obesity, β-cells secret more insulin to maintain normal glycemic homeostasis." (PMID 37152942, 2023). "Another among these genes is TNF alpha, which is involved in inflammatory processes connected to resistance to insulin, obesity, dyslipidemia and cardiovascular disease." (PMID 38248733, 2023). "This review will focus on recent insights gained from studies of two highly conserved, ubiquitous axes and how they contribute to insulin resistance and metabolic dysfunction in obesity." (PMID 37383542, 2023). "The increase in IL6 expression during exercise also suppresses hyperphagia and reduces obesity-induced hypothalamic inflammation, thereby promoting insulin and leptin sensitivity and re-establishing balances in the control of appetite and energy homeostasis." (PMID 36986146, 2023). "Despite previous research, the main impact of macrophage insulin action on obesity and related metabolic disorders is still debated." (PMID 37153549, 2023). "Preventing the aging of neutrophils via selective ablation of CXCR2, reduces the development of obesity and improves the sensitivity to insulin." (PMID 38327649, 2023). "In conclusion, metformin seems to be effective in improving insulin parameters as long as some lipid parameters in children with obesity and NAFLD." (PMID 37639015, 2023). "Obesity negatively affects insulin signaling in obese mice, as evidenced by insulin-signaling markers, including glucose transporter type 4 (Glut4) and insulin-receptor substrate 1 (Irs1), which are downregulated with HF exposure." (PMID 38137341, 2023). "Compared to the same PSMF diet given orally, the ProMoFasT is an effective and safe nutritional intervention that has a good compliance rate and results in improvements in body composition with an insulin-lowering effect among subjects with severe obesity." (PMID 38004217, 2023). "Fenretinide is a synthetic retinoid that can prevent obesity and improve insulin sensitivity in mice by directly altering retinol/retinoic acid homeostasis and inhibiting excess ceramide biosynthesis." (PMID 36894641, 2023). "Inflammation and insulin resistance, caused by obesity, is reduced in TLR4-/- mice by preventing insulin signal transduction and nitric oxide generation." (PMID 36674680, 2023). "In fact, an underlying pathophysiological condition of obesity and T2DM is the reduced biological response to insulin in peripheral tissues such as the liver, adipose tissue, and skeletal muscle." (PMID 36674935, 2023).
Obesity (continued). "LPL hydrolyzes triglyceride (TG) into fatty acid and glycerol and hepatic lipase deficiency exhibited glucose intolerance and hepatic steatosis, whereas increasing LPL rescued glucose and insulin tolerance in high fat diet-induced obesity." (PMID 37033452, 2023). "Among these, NNC0090-2746 and tirzepatide showed improved efficacy in terms of EE, insulin sensitivity and weight loss, as compared to single GLP-1R agonism in a model of diet-induced obesity." (PMID 37378828, 2023). "In our sample of youths with obesity, we found differences in insulin clearance in the fasting condition and during the OGTT between prepubertal and pubertal individuals who had lower clearance." (PMID 37834412, 2023). "The flavonoid quercetin, which is abundant in many wild vegetables, has been reported to improve insulin sensitivity, reduce adipose tissue inflammation, and enhance lipid metabolism in animal models of obesity." (PMID 37107470, 2023). "It plays vital roles in regulating glucose and lipid metabolism, adipocyte biology, insulin sensitivity, and the inflammatory response, making it closely involved in the pathophysiology and intervention of obesity and its comorbidities." (PMID 37408258, 2023). "A second measurement would also have been preferable for children with high insulin values, although hyperinsulinaemia is common among children with obesity." (PMID 37420130, 2023). "In the second approach, we identified four subgroups: cluster 1 (obesity- and age-related, 68%), cluster 2 (malnutrition-related, 8%), cluster 3 (body fat-related and insulin-resistant, 18%), and cluster 4 (ketosis-prone, 6%)." (PMID 37402743, 2023). "Obesity-induced endoplasmic reticulum stress affects insulin synthesis and disrupts proper insulin receptor synthesis, leading to impaired insulin signaling." (PMID 36671511, 2023). "Reduced obesity and hepatic steatosis further contributed to improved insulin sensitivity in the liver of adipocyte-P2Y14R KO mice." (PMID 36835211, 2023). "Unsurprisingly, exercise is seen as a powerful tool to combat the prevalence of obesity given that in obese older adults, chronic exercise training can improve insulin sensitivity, reduce inflammation, and improve body composition." (PMID 37372149, 2023). "Adipose tissue energy storage is dependent on insulin which is responsible for 5% of insulin-mediated glucose uptake in normo-weight subjects and 20% in patients with obesity." (PMID 38136564, 2023). "It was reported that ginsenoside Rb1 exerts significant anti-obesity, anti-hyperglycemic, and anti-diabetic effects by regulating glycolipid metabolism and improving insulin and leptin sensitivities." (PMID 37337262, 2023). "Compromised insulin action and/or insulin secretion contribute to the setting and maintaining conditions such as hyperglycemia, hyperlipidemia, hypertension, and obesity, all of which are standard features of MS." (PMID 37569362, 2023). "To determine how the expressions of the circRNAs were changed by obesity in the brain, we chose seven obesity-related blood serum factors, glucose, insulin, TNF-α, IL-6, PA, LA, and Chol, that mimic obesity in the brain." (PMID 37047207, 2023). "Improvements in liver parameters, glucose tolerance, and a decrease in fasting insulin levels were observed, although they were less pronounced in the lipedema group than in the overweight/obesity group." (PMID 37299581, 2023). "Consistently, in a prior randomized cross-over trail, researchers found that inulin supplementation improved insulin sensitivity and decreased Clostridia in adults with overweight and obesity." (PMID 37202792, 2023). "Analyses of CTRP knockout mice and CTRP transgenic mice gave overwhelming evidence for the relevance of the anti-inflammatory and insulin-sensitizing effects of CTRPs in autoimmune diseases, obesity, atherosclerosis and cardiac dysfunction." (PMID 36831095, 2023).